ACSL4 (acyl-CoA synthetase long chain family member 4)
Diseases named in the same sentence as ACSL4 in open-access papers (continued):
Sharing a sentence is not in itself a finding about the gene and the disease.
tumor (continued). "ACSL4 knockdown reduced 17β-estradiol-induced migration, proliferation, and invasive properties of cancer cells, whereas ACSL4 overexpression enhanced tumor growth and proliferation." (PMID 36528763, 2022). "As discussed in this review, ACSLs such as ACSL3 and ACSL4 have a double-edged effect, that is, they have both anti-tumor as well as pro-tumor effects." (PMID 36497375, 2022). "ACSL4-dependent ferroptosis establishes a link between tissue fibrosis and tumor progression, and hepatocyte ferroptosis is a breakthrough target that aggravates fibrotic and proliferative events as a promoter of HCC growth." (PMID 36238649, 2022). "Induction of ferroptosis to target therapy-resistant CRC tumour cells has been proposed, with ACSL4 potentially representing a novel biomarker for treatment." (PMID 35842572, 2022). "ACSL4 was differentially expressed in tumor tissues compared with adjacent carcinoma normal tissues." (PMID 35237519, 2022). "Due to different cancer types or different subtypes of the same cancer, ACSL4 showed different effects in promoting tumor proliferation or inhibiting cancer cell growth." (PMID 35910359, 2022). "We discovered that ACSL4, which meditated CD8+ T cell infiltration, was associated with tumor invasiveness." (PMID 34868963, 2021). "Immunohistochemical analysis of the tumor tissue confirmed the increase in ACSL4 expression after Polyphyllin III treatment." (PMID 34040532, 2021). "Recently, there has been renewed interest in the regulation of ACSL4 in oncology research because this protein plays a vital role as a hub gene in metabolism and ferroptosis of tumor cells." (PMID 34868963, 2021). "Next, we explored the prognostic value of ACSL4 for BLCA patients because there is a strong association between immune infiltration, tumor invasion, and patient survival." (PMID 34868963, 2021). "The correlation between ACSL4 expression and tumor infiltration of immune cells was analyzed using the Tumor Immune Estimation Resource database." (PMID 34868963, 2021). "Recent studies have shown that abnormal expression of ACSL4 in some tissues is related to tumor progression." (PMID 33314758, 2021). "ACSL4 showed significantly lower expression in most tumor samples using Western blot, and the result was further confirmed using immunohistochemistry." (PMID 34053456, 2021). "Acyl‐CoA synthetase long chain family member 4 (ACSL4) is closely related to tumor genesis and development in certain tissues." (PMID 33314758, 2021). "In vitro functional studies showed that knockdown of ACSL4 increased tumor survival/invasiveness and inhibited ferroptosis, while ACSL4 overexpression exhibited the opposite effects." (PMID 34053456, 2021). "To summarize, these results indicate that ACSL4 promotes tumor growth in vivo, which is consistent with our in vitro and clinical findings." (PMID 32350243, 2020). "Tumor cell-killing by TANs or in vitro differentiated neutrophils was dampened when ACSL4 expression was more effectively silenced (sh#41)." (PMID 33110073, 2020). "ACSL4 expression was significantly greater in HCC than in all other tumours and distinguished HCC from normal liver tissue with a sensitivity of 93.8% and specificity of 93.6%." (PMID 32286604, 2020). "Mice implanted with tumor cells knocked down of ACSL4 by either shRNA lived significantly longer (45% and 31%, for sh#41 and sh#42, respectively) than controls." (PMID 33110073, 2020). "Whereas higher expression of SOX10, OCLN, ACSL4, XIAP, and ERCC5 was associated with a lower risk of death from the tumor (HR < 1)." (PMID 33153038, 2020). "Functionally, ACSL4 knockdown resulted in decreased cell growth, whereas ectopic ACSL4 expression facilitated tumor formation in vitro and in vivo." (PMID 32350243, 2020). "Independent knockdown of ACSL1, ACSL3, or ACSL4 decreased cell proliferation and anchorage‐independent growth in many cancer cells and xenograft tumor growth in nude mice." (PMID 33030783, 2020).
tumor (continued). "Rescue of ferroptosis through GPX4 overexpression or ACSL4 silencing in tumor cells was reported to alleviate neutrophil-induced tumor cell killing and necrosis, inhibited tumor aggressiveness and improved mouse survival." (PMID 33679721, 2020). "Particularly so since ACSL4 is required for ferroptosis which has a potential tumour-suppressive function." (PMID 32286604, 2020). "The effect of ACSL4 on primary tumor growth was evaluated in athymic nude mice bearing ACSL4 stably depleted Huh7 and SMMC-7721 cells." (PMID 32350243, 2020). "Tumor volumes in ACSL4-depleted group were significantly reduced compared to the negative control group (p < 0.05)." (PMID 32350243, 2020). "Regarding ACSL4, a less defined pattern can be found; in fact, its expression is less homogeneous among the same tumor type." (PMID 31344914, 2019). "ACSL4 overexpression results in higher proliferation rates, higher invasion and anchorage independent growth in vitro and increased tumor burden in vivo." (PMID 31344914, 2019). "Mechanistically, the observed synergistic anti-tumor effect is mediated through the simultaneously silencing of ACSL4 and induction of GADD45B expression in HCC cells." (PMID 28900541, 2017). "We have previously reported the involvement of AA lipoxygenase-5 (LOX-5) metabolites in the action of ACSL4 on cell proliferation and tumor growth." (PMID 26536660, 2015). "ACSL4 increases proliferation, tumor growth and survival in breast, prostate, colon and liver malignancies." (PMID 26451612, 2015). "ACSL, especially ACSL4, also stimulate fatty acid entry into β-oxidation which generates not only ATP but also redox power necessary to counteract tumor oxidative stress." (PMID 26451612, 2015). "Particularly, we have demonstrated that ACSL4 promotes cell growth and tumor progression in vivo through the release of AA and its metabolization to lipoxygenase products." (PMID 26536660, 2015). "We observed a significantly increased rate of tumor growth in LNCaP xenografts expressing ACSL4 (n = 10 mice per group per clone) compared to vector controls (n = 10) (p < 0.0001) consistent with the data derived from in vitro experiments." (PMID 26636648, 2015). "Immunohistochemical analysis of tumor samples indicated a significant increase in Ki67 staining in samples derived from ACSL4-expressing cells when compared to controls." (PMID 24155918, 2013). "This inverse correlation between ACSL4 status and receptor status was significant for both studies in cell lines as well as tumor samples." (PMID 24155918, 2013). "In evaluating ACSL4 mRNA levels in tumor samples, contamination with stromal and normal tissue must be considered." (PMID 24155918, 2013). "Immunohistochemical analysis of the MCF-7 Tet-Off/ACSL4 tumor xenografts with the Ki-67 antibody revealed increased proliferation of ACSL4 overexpressing tumors with a high mitotic index as demonstrated by Ki-67 staining." (PMID 22808264, 2012). "The histological grade of the MCF-7 Tet-Off/ACSL4 tumor xenografts was evaluated by the Elston/Nottingham criteria." (PMID 22808264, 2012). "This tumor phenotype is a consequence of ACSL4 expression in the cells, since injection of MCF-7 control cells that do not overexpress ACSL4 resulted in no tumor formation." (PMID 22808264, 2012). "The first novel finding is that ACSL4 overexpression results in tumor development when injected into nude mice." (PMID 22808264, 2012). "Further, when a 4-mm3 fragment from surgically-resected MCF-7 Tet-Off/ACSL4 tumors was transplanted into acceptor female nude mice a new tumor measuring 2,500 mm3 developed 49 days after inoculation." (PMID 22808264, 2012). "The tumor growth rate of MCF-7 Tet-Off/ACSL4 tumor xenografts between days 45 and 70 was significantly higher than that in doxycycline-treated animals and than that in animals inoculated by inoculation with MCF-7 Tet-Off empty vector cells." (PMID 22808264, 2012).
tumor (continued). "Additionally, a subcutaneous xenograft mice model was established to validate the in vivo impact of ACSL4, revealing ACSL4 silencing impaired tumor growth in the OS xenograft mice." (PMID 38564125, 2025). "Emerging evidence suggests that ACSL4 may influence cancer development and progression by influencing tumor growth, metastasis, lipid metabolism, drug resistance, radioresistance, and cell death pathways." (PMID 41188993, 2025). "The downregulation of TFRC leads to reduced iron transport, and the low expression of ACSL4 impairs the catalysis of the substrates necessary for the formation of lipid hydroperoxides, thereby reducing ferroptosis-mediated cell death in tumor cells." (PMID 41011250, 2025). "Finally, to investigate the effects of ACSL4 and miR-145-5p on tumor growth in vivo, we constructed a subcutaneous transplantation tumor model." (PMID 39652084, 2025). "Additionally, overexpression of miR-145-5p and silencing ACSL4 were effective in inhibiting tumor growth in vivo." (PMID 39652084, 2025). "Given the high expression of ACSL4 in various human tumors, targeting lipid peroxidation with ACSL4 as the focal point may pave a new path in tumor therapy." (PMID 40932861, 2025). "Similarly, ACSL4-dependent tumor ferroptosis, induced by the combined effects of IFN-γ and arachidonic acid, also elicits CD8 + T cell-dependent antitumor immunity." (PMID 41326356, 2025). "Finally, we will summarize and discuss potential small molecule compounds targeting ACSL4 and lipid peroxidation for tumor prevention and treatment, aiming to provide new ideas and directions for future clinical treatment and drug development." (PMID 40932861, 2025). "OS tumor tissues was strong positive for ACSL4 as compared to para-carcinoma tissues." (PMID 38564125, 2025). "Although the role of ACSL4 in regulating tumor ferroptosis is well-documented, its cooperative mechanisms with other proteins remain unclear." (PMID 40756764, 2025). "Moreover, CD8+ T cells can trigger ACSL4-dependent tumor ferroptosis by utilizing IFN-γ and arachidonic acid, thus elevating ICB cancer immunotherapy." (PMID 39851538, 2025). "Interestingly, the increased membrane fluidity induced by ACSL4 simultaneously enhances the sensitivity of metastatic tumor cells to ferroptosis, highlighting its dual role as both a metastasis promoter and a ferroptosis sensitizer." (PMID 40919170, 2025). "However, energy crisis-induced AMPK upregulation is known to inhibit ACSL4-mediated PUFA synthesis to enhance the ferroptosis resistance of tumor cells." (PMID 41041050, 2025). "Concurrently, IFNγ can upregulate Acyl-CoA Synthetase Long Chain Family Member 4 expression through STAT1/IRF1 signaling, facilitating the integration of tumor microenvironment-associated arachidonic acid into phospholipids, inducing ferroptosis in tumor cells." (PMID 40136510, 2025). "This suggests that ACSL4 downregulation may aid tumor cells in avoiding ferroptosis, since lower expression of ACSL4 depletes the cell membrane of reactive PUFANs and decreases susceptibility to peroxidative damage." (PMID 41369416, 2025). "Consequently, therapeutic strategies targeting ACSL4 must be tailored to the specific tumor microenvironment." (PMID 40510158, 2025). "However, some studies revealed that AA assumes an anti-tumor role through three mechanisms: facilitating tumor cell ferroptosis induced by ACSL4, enhancing the anti-tumor CD8 + T-cell response, and rendering tumor cells more responsive to checkpoint therapy." (PMID 40075313, 2025). "For instance, research has shown that T cell-derived interferon-gamma (IFNγ), when combined with arachidonic acid (AA), prompts ferroptosis in tumor cells by upregulating ACSL4 and altering lipid compositions, thereby sensitizing them to iron-dependent cell death." (PMID 39150660, 2025).
tumor (continued). "We further confirmed by western blotting that IKE-treated TIPE2−/− tumor MDSCs profoundly enhanced the key ferroptosis defense proteins SLC7A11 and GPX4, but immensely lowered the main lipid peroxidation trigger protein ACSL4 when compared to IKE-treated WT tumor MDSCs." (PMID 39851538, 2025). "Inhibition of ACSL4 suppresses tumor invasion by mitigating ferroptosis." (PMID 41288931, 2025). "One study reported that lower expression of ACSL4 was associated with decreased survival, increased tumor size, and higher metastatic rates of malignant pulmonary nodules." (PMID 41369416, 2025). "Increased levels of ferroptosis driven by ACSL4 enhance tumor sensitivity to PD-1 blockade therapy." (PMID 40756764, 2025). "At the same time, STAT1 forms a complex with interferon regulatory factor 1 (IRF1), upregulates ACSL4, and promotes the integration of polyunsaturated fatty acids (such as arachidonic acid) into the phospholipids of tumor cell membranes, significantly increasing lipid peroxidation sensitivity." (PMID 40535125, 2025). "Furthermore, ACSL4 knockdown suppressed OS cell malignant phenotypes in vitro and tumor growth in vivo." (PMID 38564125, 2025). "In addition, it is undeniable that current study reveals a certain degree of contradiction regarding the role of ACSL4, ferroptosis, and cancer, as ACSL4-mediated ferroptosis appears to exert a bidirectional effect in tumor progression." (PMID 41288931, 2025). "In addition, we constructed a mouse subcutaneous transplantation tumor model and found that overexpression of miR-145-5p and silencing of ACSL4 both promoted CD8+ T cell infiltration in HCC and inhibited malignant progression and immune escape in HCC." (PMID 39652084, 2025). "Downregulating ACSL4 potentiated tumor cells to irradiation and inhibited cell migration." (PMID 41188993, 2025). "The primary role of ACSL4 is to promote energy production via β-oxidation through the generation of substrates for entry into this process, rather than lipid synthesis, making it a specific target for disrupting tumor metabolism." (PMID 40507798, 2025). "Additionally, patients with high ACSL4 expression in pre-treatment tumour tissues also exhibited complete or partial responses to sorafenib, which is a first-line treatment for advanced HCC." (PMID 41154605, 2025). "When being internalized by tumor cells, PGHM-R-Fe could significantly upregulate the expression of ACSL4 and increase the production of ferroptosis-susceptible PUFAs." (PMID 39744220, 2025). "Moreover, radiation and cisplatin induced much less cell death in tumor cells re-expressing ACSL4-T679A." (PMID 38720107, 2024). "Additionally, the activation of ACSL4 (Acyl-CoA Synthetase Long-Chain Family Member 4) by M1 macrophages increases the oxidative sensitivity of tumor cell membrane phospholipids, thereby promoting ferroptosis." (PMID 39575419, 2024). "Additionally, ACSL4 knockout or knockdown in human breast cancer cells not only inhibits tumour growth and metastasis in vivo but also enhances sensitivity to doxorubicin." (PMID 38610991, 2024). "IHC staining revealed that POL increased the levels of ACSL4 in tumor tissues." (PMID 38503553, 2024). "Moreover, the levels of PCK2 and p-ACSL4(T679) were downregulated in TRCs compared to bulk tumor cells in multiple cell lines as well." (PMID 38720107, 2024). "ACSL4 can promote tumor progression in various cancer types." (PMID 39335604, 2024). "In addition, IFN-γ stimulates ACSL4 and alters the lipid profile of tumour cells, which promotes ACSL4-dependent tumour ferroptosis." (PMID 38993573, 2024). "Additionally, plant metabolites and derivatives can regulate ferroptosis by targeting SLC7A11, GPX4, and ACSL4 and influence the immune status in the tumor microenvironment, providing new insights and directions for TCMs in cancer treatment." (PMID 38292937, 2024).
tumor (continued). "In addition, high levels of ACSL4 and SLC7A11 in CCA sera were significantly associated with advanced tumor staging, poorer prognosis parameters, and a short survival time." (PMID 39335604, 2024). "This translocation of miR-22-3p led to an attenuated tumor cell response to erastin-induced ferroptotic death, an effect that was achieved through the suppression of its proferroptotic target gene acyl-CoA synthetase long-chain family member 4 (ACSL4)." (PMID 39634266, 2024). "Notably, ACSL4 expression inversely correlated with the presence of tumor necrosis in HCC tissues (P = 0.007), suggesting a potential role of ACSL4 in tumor physiology and response to therapy." (PMID 39563427, 2024). "Notably, bulk tumor cells with ACSL4 knockdown exhibited similar RSL3-induced cell death to that of TRCs with or without ACSL4 knockdown." (PMID 38720107, 2024). "Recent investigations have demonstrated that Interferon-gamma (IFNγ) promotes the expression of ACSL4, leading to alterations in lipid profiles within tumor cells, consequently increasing the presence of arachidonic acid (AA) in phospholipids containing C16 and C18 acyl chains." (PMID 39420203, 2024). "Notably, ACSL4-KO inhibited the growth of tumor and canagliflozin further hindered the growth of ACSL4-KO xenografts." (PMID 39563427, 2024). "However, cells counteract this risk by inhibiting ACSL4 expression and reducing the incorporation of ferroptosis substrate PUFA into the membrane, thus allowing cells to escape ferroptosis and promote tumour progression." (PMID 38736108, 2024). "It has been reported that ACSL4 plays a tumor-suppressive role and could be a potential therapeutic target in GC." (PMID 38370339, 2024). "In addition, a higher expression of ACSL1 and ACSL5 was significantly related to a low tumor grade (ACSL1, p = 0.023; ACSL5, p = 0.025), while a higher expression of ACSL4 was significantly associated with a high grade (p = 0.009)." (PMID 38539505, 2024). "Additionally, IFNγ, in conjunction with arachidonic acid, induces tumor cell ferroptosis through ACSL4, highlighting the potential of targeting tumor ferroptosis metabolism to enhance cancer immunotherapy." (PMID 39273090, 2024). "High levels of ACSL4 and SLC7A11 in CCA sera were both significantly associated with advanced tumor stages and abnormal liver function test results, indicating that they could be used as a reliable prognostic biomarker panel in patients with CCA." (PMID 39335604, 2024). "For example, membrane-associated ring-CH-type finger 6 (MARCHF6), an E3 ubiquitin ligase, interacts with nicotinamide adenine dinucleotide phosphate (NADPH) to enhance its own activity while mediating the degradation of ACSL4 to inhibit ferroptosis in tumor cells." (PMID 37372148, 2023). "Cardiac-specific block of miR-22-3p biogenesis or inhibition of target gene ACSL4 activation may be a novel effective therapeutic avenue to block exosome-mediated pathological communications between MI heart and tumor tissue." (PMID 36967385, 2023). "Further exploration of the acetylation function of ACSL4 could provide a potential avenue for tumor treatment and also offer an important foundation for drug development in other metabolic disorders." (PMID 37372148, 2023). "Interestingly, although high ACSL4 levels positively correlate with sorafenib sensitivity in vitro, reduced miR-211-5p expression leading to increased ACSL4 levels will promote tumor proliferation and invasion." (PMID 37627215, 2023). "Notably, the AA level in tumor interstitial fluids is higher than that in peripheral blood, and AA in the tumor microenvironment is primarily incorporated into PE via ACSL4, as evidenced by AA-d5 tracing experiments." (PMID 37612411, 2023). "However, targeting ACSL4 can regulate tumor progression, so ACSL4 is very likely to be a novel target for treatment." (PMID 37056351, 2023). "As previous reported, ACSL4 could promote or suppress tumor growth depending on the specific types of cancer." (PMID 37193981, 2023).